HULC (hepatocellular carcinoma up-regulated long non-coding RNA)
Diseases named in the same sentence as HULC in open-access papers (continued):
Sharing a sentence is not in itself a finding about the gene and the disease.
tumor (58 papers, 2012 to 2025). "Our meta-analysis confirms the association between HULC expression levels and survival prognosis in patients with digestive system tumors, and adds the analysis of tumor size, number of tumors, differentiation, age and gender of patients." (PMID 35183058, 2022). "The upregulation of HULC is associated with tumor proliferation and is effected via downregulation of the p18 tumor suppressor." (PMID 31056726, 2019). "Here, we evaluated the expression of HULC, which is an lncRNA that is associated with the tumor metastatic process, and assessed its potential role as a prognostic marker in OS." (PMID 27253450, 2016). "Although increased levels of HULC expression have been implicated in tumor invasion and metastasis, the exact mechanisms and downstream mediators of these effects remain to be elucidated." (PMID 27285757, 2016). "High serum HULC expression levels were significantly associated with tumor size (P = 0.001), lymph node metastasis (P = 0.021), distant metastasis (P = 0.017), and tumor-node-metastasis stage (P = 0.002)." (PMID 27322075, 2016). "In conclusion, contributing to decreased susceptibility to vascular invasion, upregulation of HULC in tumor tissues was positively associated with HCC survival." (PMID 26136615, 2015). "Until now, only a few circulating lncRNAs (for example, PCA3 and HULC) have been identified and have been determined to be good tumor diagnostic markers." (PMID 26674525, 2015). "In addition, serum HULC levels expression was associated with tumor size, lymph node metastasis, distant metastasis and H. pylori, a strong risk factor for both GC development and progression." (PMID 29599934, 2018). "For example, the oncogenic HULC is significantly upregulated in plasma of patients as well the HCC tumor tissues; thus, it could serve as a novel diagnostic biomarker for HCC." (PMID 30105249, 2018). "Furthermore, HULC overexpression was linked with tumor size, clinical TNM stage, and recurrence and overall survival (OS) in HCC." (PMID 30105249, 2018). "As research has progressed, HULC has been found to be abnormally expressed in a range of digestive system malignancies, where it contributes to the regulation of tumor cell behavior." (PMID 40909946, 2025). "Overall, HULC interacts with genes, RNA, and proteins to promote tumor cell metabolism reprogramming(Warburg effect), and an anti-apoptotic phenotype." (PMID 40909946, 2025). "In HBV-related HCC, metformin has been shown to inhibit tumor cell proliferation by negatively regulating the HULC/p18/miR-200a/ZEB1 signaling pathway." (PMID 40909946, 2025). "In vivo, using PC xenografts in nude mice demonstrated that HULC knockdown significantly suppressed tumor growth compared to controls." (PMID 40909946, 2025). "Bioinformatics analysis of 36 CCA tumor tissues and 9 normal control tissues from WMU cohort revealed that HULC was significantly upregulated and strongly associated with shorter overall survival in CCA patients." (PMID 40909946, 2025). "Nine studies reported the relationship between the expression level of HULC and the clinicopathological characteristics of patients, such as age, gender, tumor size, TNM stage and tumor differentiation." (PMID 35183058, 2022). "Previous reports have shown that HULC was involved in various processes of tumor formation and metastasis." (PMID 36213832, 2022). "Recently, studies have shown that HULC is overexpressed in digestive system tumors to promote tumor development." (PMID 35183058, 2022). "HULC was identified to promote lymph node metastasis; however, low expression of HULC seemed to be correlated with high levels of tumor size, distant metastases, and pathologic stage." (PMID 36438902, 2022). "There are several oncogenic or tumor suppressive lncRNAs that have been associated with 5-FU resistance, such as FAM83H-AS1, MACC-AS1, HULC, ANRIL, XLOC-006753, FGD5-AS1 and LE1GC." (PMID 34345204, 2021).
tumor (continued). "Consistent with the results from cell assays, the overexpression of HULC increased tumor growth in mice, and more lactate was detected from the tumors formed by HULC overexpressing cells than by control cells." (PMID 32572027, 2020). "It reveals the key molecular signaling pathways for HULC and provides important basic information for finding effective tumor therapeutic targets based on HULC." (PMID 31900225, 2020). "We assumed that candidate tumor-suppressing miRNAs would inhibit EMT pathway through targeting HULC." (PMID 32656089, 2020). "Up-regulated HULC promotes cellular proliferation, migration, and invasion, while silencing of HULC inhibits tumor growth and enhances chemotherapy-induced apoptosis." (PMID 32010942, 2020). "Conclusion: β-Elemene performs as a tumor suppressor and modulator of HULC-mediated apoptotic pathway in DLBCL and will be an alternative candidate for clinical application." (PMID 32010942, 2020). "A meta-analysis indicated that HULC overexpression is a predictor of poor prognosis in various cancer types and the higher incidence of tumor metastasis." (PMID 32010942, 2020). "HULC promotes tumor growth and progression in several cancers by mediating multiple signaling pathways and interacting with miRNAs." (PMID 32010942, 2020). "We observed higher levels of HULC in HCC tissues compared with controls (adjacent non-tumor liver tissue) in two Gene Expression Omnibus (GEO) datasets (GSE39791 and GSE76427), and The Cancer Genome Atlas (TCGA) cohort." (PMID 31645479, 2019). "Knockdown of HULC in HCC cell lines represses cell proliferation, invasion, and migration, and promotes cell apoptosis, whereas HULC overexpression promotes Hep3B cells growth and increases the xenograft tumor weight and formation rate." (PMID 31480503, 2019). "Collectively, these results showed that HULC is crucial for tumour growth and promotes the EMT process." (PMID 30677230, 2019). "On the other hand, when HULC was overexpressed, the xenograft tumor appearance time was significantly decreased compared to the corresponding control group (6.017 ± 1.049 days versus 10.583 ± 2.873 days, P = 0.003873 < 0.01)." (PMID 29895332, 2018). "Among them, H19 and another five lncRNAs (HOTAIR, PVT1, MALAT1, GHET1 and HULC) were significantly higher in tumor tissues compared to matched normal samples." (PMID 29599934, 2018). "Though the role of H19 in tumor initiation and progression has long been a subject of controversy and HULC is highly over expressed in serval tumors, H19 and HULC were significantly downregulated in iCCA tissues compared with normal tissues in both studies." (PMID 28427159, 2017). "In conclusion, since high levels of HULC expression in multiple cancers are associated with poor OS, LNM, DM and tumor stage, it is a promising prognostic biomarker in cancer." (PMID 28199963, 2017). "When HULC was overexpressed, the xenograft tumor weight increased approximately two folds when compared to the corresponding control group (1.34 grams versus 0.68 grams, t-test, P < 0.01)." (PMID 27782152, 2016). "Mounting evidence indicates that HULC plays an essential role in liver tumor development, and HULC, as an oncogenic factor in human tumor progression, is upregulated in HCC." (PMID 27285757, 2016). "Congruously, ELISA showed that the hemoglobin content in tumor tissues derived from HULC-overexpressed group was higher than that from SPHK1-knockdown group, suggesting that HULC enhances tumor angiogenesis through SPHK1." (PMID 26540633, 2016). "It has been reported that HULC can promote tumor invasion and metastasis of HCC, but its function and mechanism of action in HCC have not been elucidated." (PMID 27285757, 2016). "Among them, HOTAIR, PVT1, H19, MALAT1, GHET1 and HULC were significantly higher in tumor tissues compared with control tissues." (PMID 26096073, 2015). "Our results showed that HULC is markedly up-regulated in the HCC tumor tissues and in plasma of HCC patients." (PMID 23762823, 2013).
tumor (continued). "We examined the expression level of HULC in HCC tumor tissues and liver tissues obtained from healthy volunteers and the matching plasma of these two groups using a real-time quantitative RT-PCR." (PMID 23762823, 2013). "Further, the expression of HULC in 30 HCC tumor samples and 20 healthy control liver tissue samples were determined." (PMID 23762823, 2013). "In this study, we demonstrate that lncRNA HULC is overexpressed in HCC tumor tissues compared to healthy liver tissues." (PMID 23762823, 2013). "Our data suggest that HULC expression in HCC is likely to be associated with the aggressiveness and the progression of the tumor." (PMID 23762823, 2013). "In a murine xenograft model, depletion of HULC reduced tumor growth and suppressed EMT." (PMID 40909946, 2025). "Similarly, the expression of HULC was also increased in tumor cell lines Saos-2, MG63, and U-2OS in contrast to normal cell (hFOB 1.19)." (PMID 36213832, 2022). "Moreover, another study found that HULC was aberrantly upregulated in HCC tissues and associated with the tumor node and metastases (TNM) stage, HCC recurrence, intra-hepatic metastases, and postoperative survival." (PMID 36140836, 2022). "We predicted that the increased expression (~6 folds) of HULC in ccRCC tumor tissues might promote lymphatic metastasis and poor prognosis." (PMID 36438902, 2022). "Experiments in the contexts of various neoplasms have indicated an anti-apoptotic role for HULC." (PMID 34868009, 2021). "Moreover, HBV X protein (HBx), an oncogenic viral protein, positively correlates with the levels of HULC in HCC tumor tissues, and HBx induces the transcription of HULC via transcription factor CREB18,19." (PMID 32572027, 2020). "We recently reported that lncRNA HULC could promote tumor cell invasion and migration via induction of the EMT pathway in human PDAC cells." (PMID 32656089, 2020). "Based on this knowledge, we aimed to identify other interactions between HULC and miRNAs that could modulate tumor cell invasion and migration via EMT regulation." (PMID 32656089, 2020). "Notably, quantification of subcutaneous tumorigenesis in nude mice confirmed that HULC down‐regulation inhibits tumour growth and the EMT process in vivo." (PMID 30677230, 2019). "In addition to the tumor tissues, significantly greater levels of HULC were also found in HCC cell lines and plasma of patients, indicating its potential role as a biomarker of HCC." (PMID 30105249, 2018). "Taken together, these findings indicate that HULC may be a potential tumor biomarker for early diagnosis, progression monitoring and GC prognosis of GC." (PMID 29599934, 2018). "In this study, we demonstrated the role of HULC in tumor angiogenesis in vitro and in vivo." (PMID 26540633, 2016). "The identification of this novel pathway that links high expression levels of HULC with EMT in HCC cells may serve as the foundation for the development of novel anti-tumor therapeutics." (PMID 27285757, 2016). "Meanwhile, HULC promoted tumor growth and intrahepatic metastasis in vivo." (PMID 27285757, 2016). "Taken together, we conclude that HULC promotes tumor angiogenesis in vitro and in vivo." (PMID 26540633, 2016). "The high levels of HULC expression which contribute to tumor invasion and metastasis might be related to EMT." (PMID 27285757, 2016). "For this analysis, the relative HULC expression in tumor tissues from the 38 HCC patients were classified into two groups: HULC(L) - Low relative levels of HULC mRNA (n=15, fold change < 7.0) and HULC(H) - High relative levels of HULC mRNA (n=23, fold change ≥ 7.0)." (PMID 27285757, 2016). "Our present study indicates that circulating HULC may represent a novel serum tumor marker for early diagnosis and monitoring progression and prognosis of GC." (PMID 27322075, 2016).
tumor (continued). "However, the GO findings were unexpected in that we identified some up-regulated proteins in cell activity, such as actin filament bundles and actin binding after HULC knockdown, that indicate that HULC suppression can promote tumor migration and invasion, which contradicts our functional results." (PMID 34131250, 2021). "It was later discovered that HULC could promote tumor growth as a lncRNA7." (PMID 34131250, 2021). "Therefore, we hypothesized that HULC plays an important role in angiogenesis as well as tumor aggravation in vitro and in vivo." (PMID 26894862, 2016). "Mechanistically, HULC induces malignant phenotypes such as Warburg effect and EMT in tumor cells through interactions with genes, RNA, and proteins." (PMID 40909946, 2025). "Studies have demonstrated that HULC can directly bind to and increase the phosphorylation of both LDHA and PKM2, thereby enhancing glycolysis in HCC cell lines and facilitating tumor progression." (PMID 40909946, 2025). "In radiation-induced liver cancer, HULC was found to downregulate the expression of the nearby gene CDKN1 through complementary base pairing, thereby affecting tumor progression." (PMID 40909946, 2025). "Mechanistically, HULC induces EMT via the miR-200a-3p/ZEB1 signaling pathway, thereby facilitating tumor progression and metastasis." (PMID 40909946, 2025). "HULC is highly expressed in HCC, and its inhibition can reduce tumor growth and improve chemotherapy sensitivity." (PMID 39857631, 2024). "As expected, many common tumor‐related lncRNAs, such as MALAT1, NEAT1, HULC, and PVT1, were identified in the H3K27ac chromatin immunoprecipitation sequencing (ChIP‐seq) data." (PMID 36307901, 2022). "In contrast, lncRNA MALAT-1 and HULC were found up-regulated in HCC and promote tumor growth, metastasis and drug resistance by interacting with several pathways closely relevant in HCC progression." (PMID 34285143, 2021). "Our final panel consisted of seven up‐regulated DElncRNAs (CCAT1, CCAT2, H19, HOTAIR, HULC, MALAT1, PCAT1), which were also known as oncolncRNAs and three down‐regulated lncRNAs (MEG3, PTENP1, and TUSC7) as tumor suppressor lncRNAs (tslncRNAs)." (PMID 33094859, 2021). "Other oncogenic lncRNAs such as H19, HULC, SNHG12, and HOTAIR also demonstrated their regulatory functions in promoting cancer cell proliferation, inhibiting apoptosis, and aggravating tumor progression." (PMID 34456631, 2021). "Our results indicate that HULC knockdown alters the protein profile of GBM cells, which likely contributed to tumor pathogenesis." (PMID 34131250, 2021). "HULC not only increases the expression of E2F1, but also sequesters miR-107, which is an inhibitor of E2F1, to promote tumor angiogenesis." (PMID 31480503, 2019). "Actually, numerous lncRNAs function as oncogenes or tumor-suppressor genes, which were reported to be involved in metastasis and prognosis of HCC, such as MEG3, GAS5, HOTAIR, HULC, H19, and MALAT1." (PMID 31500187, 2019). "We also found that HULC promotes the proliferation, migration, and invasion of HCC cells in vitro, and xenograft tumor growth in vivo." (PMID 31645479, 2019). "Our results also demonstrated in vitro that HULC down‐regulation can inhibit OSCC cell proliferation, migration, and invasion and induce tumour‐cell apoptosis." (PMID 30677230, 2019). "Lastly, to investigate the potential of HULC as a new OSCC therapeutic target, we established a xenograft tumour model by using the SCC15 cell line in nude mice." (PMID 30677230, 2019). "We also highlighted common long non-coding RNA molecules such as HULC, HOTAIR, MALAT1, XIST, H19 and GAS5, which mediate the two-way interactions between stroma and tumor." (PMID 28392501, 2017). "Hämmerle and colleagues found that HULC up‐regulation was most prominent in low‐stage HCC and progressively decreased along advancing tumour stages." (PMID 27781386, 2017).
tumor (continued). "In another study, Wang and colleagues verified the up‐regulation of HULC in HCC using 14 pairs of tumour and para‐tumour tissues by real‐time reverse transcription (RT)‐PCR." (PMID 27781386, 2017). "HULC was also recently shown to enhance epithelial-mesenchymal transition (EMT), which contributes to tumor metastasis and recurrence in HCC via a signaling pathway involving zinc finger E-box binding homeobox 1 (ZEB1) and miR-200a-3p." (PMID 30159431, 2017). "On the other hand, when both HULC and MALAT1 were overexpressed, the average xenograft tumor weight increased to approximately 3.5 folds of the control weight (2.23 grams versus 0.68, t-test, P < 0.01)." (PMID 27782152, 2016). "Our data suggested that a positive correlation existed between the expression of HULC and some EMT features, which likely contribute to the observed aggravation of tumor metastasis in HCC." (PMID 27285757, 2016). "HULC and/or MALAT1 overexpression resulted in early xenograft tumor formation compared to the control group (7.2days, 7.5days, 5.8 days versus 10.8days, respectively t-test, P < 0.01)." (PMID 27782152, 2016). "While there is an increasing interest in lncRNAs, to date only a handful has been investigated in HCC, including highly up-regulated in HCC, such as HULC, HOTAIR, H19, HEIH and MVIH, and down-regulated in tumor tissues, such as MEG3, hDreh and LET." (PMID 26674525, 2015). "HULC has been found to bind directly to and increase the phosphorylation of key glycolytic enzymes LDHA and PKM2, thereby promoting glycolysis and enhancing tumor progression." (PMID 40909946, 2025). "Mechanistically, HULC exerts its oncogenic effects by interacting with genes, RNA, and proteins to promoting the Warburg effect, and inducing epithelial-mesenchymal transition (EMT), thereby facilitating tumor progression." (PMID 40909946, 2025). "Both HULC and Linc00152 were upregulated in the plasma of patients with HCC, and the expression of HULC and Linc00152 in plasma was positively correlated with the expression in tumor tissue." (PMID 33777736, 2021). "Altogether, miR-622 may attenuate tumor cell invasion and migration by inhibition of EMT via targeting HULC in PDAC cells." (PMID 32656089, 2020). "The analysis results show that HULC is significantly upregulated in HCC tumor samples as compared with the adjacent non-tumorous tissues." (PMID 32572027, 2020). "Our study revealed that miR-622 was down-regulated by TGF-β1 and could attenuate tumor migration and invasion via suppression of EMT by targeting HULC." (PMID 32656089, 2020). "Another lncRNA HULC was also found to be overexpressed in HCC tissues and correlate with low-grade and low-stage HCC, indicating a functional role of HULC in the early stages of tumor development." (PMID 29954406, 2018). "HULC was further found to sequester miR-107, a known regulator of E2F1, resulting in a cascade of upregulated E2F1, increased SPHK1 activation, and eventually, tumor angiogenesis." (PMID 30159431, 2017). "Moreover, HULC contributes to ZEB1-induced epithelial-mesenchymal transition (EMT), a requirement for tumor invasion and metastasis that plays a key role in cancer progression." (PMID 27285757, 2016). "Meanwhile, the other 13 lncRNAs (AC008781.2, HULC, AC100839.1, CRAT37, LINC01198, LINC01482, SMAD1‐AS2, TH2LCRR, DISC1‐IT1, ABCC5‐AS1, NFIA‐AS1, AC007431.1, AC012494.1) were up‐regulated and hypomethylated in CC tumor group which confirmed our previous MethylRad sequencing results." (PMID 32869528, 2020). "However, to date, there exists no direct evidence regarding the mechanisms through which HULC mediates tumor cell invasion and metastasis." (PMID 27285757, 2016). "HOTAIR, MALAT1, HULC, and UCA1 were similarly expressed between tumor tissues and nontumor tissues in HCC patients (P = 0.448, 0.138, 0.085, and 0.373, resp)." (PMID 26136615, 2015).